APP (amyloid beta precursor protein)
Diseases named in the same sentence as APP in open-access papers (continued):
Sharing a sentence is not in itself a finding about the gene and the disease.
epilepsy (continued). "To assess the seizure susceptibility in the early stage of AD, we established the acute and chronic PTZ chemical-kindling epilepsy models in 4-month-old APP and WT mice." (PMID 38388921, 2024). "Risk biomarkers, including a CD1 background or carrying an APP/PS1 mutation, indicate a greater susceptibility towards epilepsy." (PMID 34827090, 2021). "We performed ChIP-sequencing to assess the repertoire of ΔFosB target genes in APP mice and in pilocarpine-treated wildtype mice (Pilo mice), a pharmacological model of epilepsy." (PMID 32536852, 2020). "We found that of the 2,839 genes bound by ΔFosB in APP mice, there was a significant overlap of 121 genes with epilepsy-related genes (p = 0.001)." (PMID 32536852, 2020). "Elevated expression of APP and its processing enzymes, β-APP expression, and Aβ1-40 and Aβ1-42 levels in experimental and human epilepsy suggest a possible role in mediating neurodegeneration in epilepsy." (PMID 32545604, 2020). "Other authors have reported that topiramate (TPM) and levetiracetam (LEV), two classical drugs used in the management of epilepsy, alleviated behavioral deficits and diminished senile plaques in APP/PS1 mice." (PMID 24679124, 2014). "The analysis of an experimental model of epilepsy confirmed that the coexpression between APP and many of the candidates can be detected also in CNS tissues." (PMID 21829458, 2011). "Among these are RACK1 (involved in neuronal excitation), TSC1 (control of axon formation, epilepsy), APP (seizure susceptibility), HSPBAP1 (upregulated in epilepsy patients) and p190 RhoGAPs (involved in neuronal differentiation and process outgrowth)." (PMID 22016787, 2011). "Furthermore, we confirmed the inhibitory effect of NRG1 on epilepsy in APP mice via intracerebroventricular infusion." (PMID 38388921, 2024). "We hypothesize that altered APP processing and accumulation of Aβ detected in epilepsy and traumatic brain injury are the major pathophysiological mechanisms that link autism with some of its co-morbidities." (PMID 37305553, 2023). "ΔFosB target genes in APP mice were more numerous and were involved in epilepsy-relevant functions including excitability and neurogenesis, whereas ΔFosB target genes in NTG mice were less numerous and were involved in basal functions like maintenance of cell polarity." (PMID 32536852, 2020). "The 5 Hub genes, including C3, CD44, ANXA2, HTR1E, and APP, were also identified as the BottleNeck genes, that is, they are Hub-BottleNeck genes, indicating that they are much more important than the remaining Hub genes in the pathogenesis of epilepsy in PT." (PMID 33123575, 2020). "We therefore assessed whether ∆FosB gene targets in APP mice are involved in epilepsy-related pathways by comparing our list of gene targets to EpilepsyGene, a database cataloging 499 genes and 3931 gene variants that have been implicated in clinical epilepsy." (PMID 29408867, 2018). "Likewise, 12/28 genes have been implicated in epilepsy or have a close family member established to increase risk including SCN2B, CALM1, CALM2, and APP." (PMID 26824476, 2016). "Behavioural disturbances, epilepsy, myoclonus, or CAA (specific for APP mutations) may help in addressing diagnosis." (PMID 24377094, 2013). "Because HCN1 associates with amyloid-β precursor protein (APP) and X11/X11L in the brain, genetic deficiency of X11/X11L may induce aberrant HCN1 distribution along with epilepsy." (PMID 23034178, 2012). "We also note that both J20 and APP/PS1 mice have prominent epilepsy, and our divergent findings with ethosuximide and brivaracetam with respect to reversal of impairments in spatial memory may be explained by the efficacy of treating partial versus generalized seizures." (PMID 25945128, 2015). "Proteomic data showed that total levels of APP and MAPT were unchanged in epilepsy." (PMID 38289539, 2024).
epilepsy (continued). "The expression of APP, but not the level of APP mRNA, is higher in temporal lobe and hippocampi from patients undergoing epilepsy surgery compared to controls." (PMID 29506031, 2018). "However we should note that because few participants had epilepsy the confidence intervals for this phenotype are large and, although we do not detect any effect, we cannot rule out the possibility that LOF variants in APP or MAPT might have a substantial effect on risk." (PMID 41123760, 2025). "The same group, in 2014, evaluated the CSF levels of different isoforms of β-amyloid (Aβ peptides: Abx-38, Abx-40, Abx-42, and Ab1-42), soluble APP fragments (sAPP-α/β), t-TAU, p-TAU, and heart-type fatty acid binding protein (H-FABP) in patients with epilepsy, including four with non-convulsive SE." (PMID 37569895, 2023).
amyotrophic lateral sclerosis (38 papers, 2011 to 2025). Amyotrophic lateral sclerosis (ALS) is a neurodegenerative disease characterized by progressive muscular paralysis reflecting degeneration of motor neurons in the primary motor cortex, corticospinal tracts, brainstem and spinal cord. "Among these four variants, PSEN1 p.R269H and TARDBP p.G287S had been previously reported as causes of AD and amyotrophic lateral sclerosis (ALS), respectively, while the remaining two variants in the APP and PSEN2 genes were novel." (PMID 40813364, 2025). "AEP has previously been reported to cleave aggregate-forming proteins, such as amyloid precursor protein (APP), microtubule associated protein tau (MAPT) and TAR-DNA binding protein 43 (TDP43) and is also implicated in an FTLD-related disorder, amyotrophic lateral sclerosis (ALS)." (PMID 34344440, 2021). "HPRT1 encodes hypoxanthine phosphoribosyltransferase 1, and mutated HPRT1 affects amyloid precursor protein (APP) gene expression in AD and amyotrophic lateral sclerosis (ALS)." (PMID 32461378, 2020). "The BBB-permeable Cx32 HC blocker INI-0602 not only ameliorated symptoms in two amyotrophic lateral sclerosis (ALS) mouse models, but also improved memory deficits in the APP/PS1 transgenic model of AD." (PMID 27713688, 2016).
autism (35 papers, 2010 to 2025). Persistent deficits in social interaction and communication and interaction as well as a markedly restricted repertoire of activity and interest as well as repetitive patterns of behavior. "In contrast, miR-150-5p, which targets the autism-associated Foxp169 transcript, declined with age in live human neurons, Klotho KO and by both age and APP pathology in AD mice models." (PMID 38862813, 2024). "Previous studies have identified 206 autism-susceptibility genes that converge on the amyloid precursor protein (APP) metabolic pathway." (PMID 35350428, 2022). "Recent studies indicate that non-amyloidogenic cleavage of the amyloid-β (Aβ) peptide precursor (APP) with α and γ secretases is linked to several developmental disorders, including autism and FXS." (PMID 22567102, 2012). "Thus, early developmental alterations of APP processing and Aβ accumulation associated with autism promote the incidence of epileptic episodes." (PMID 37305553, 2023). "Nevertheless, it remains unclear whether APP and its metabolites are involved in the pathophysiological pathways underlying other autism phenotypes." (PMID 35350428, 2022). "Autism, the most frequent neurodevelopmental disorder of a very complex etiopathology, is associated with dysregulation of cellular homeostatic mechanisms, including processing of amyloid-β precursor protein (APP)." (PMID 32345355, 2020). "We speculate that the underlying molecular abnormalities that influence APP’s contribution to autism are epigenetic markers overlaid onto potentially vulnerable gene sequences due to environmental influence." (PMID 23801940, 2013). "APP, along with presenilin and indeed numerous other factors, may exert effects on the synapse through actions on glial function, leading to either excess synapses (as occurs in autism) or synapse loss (as occurs in AD)." (PMID 25231068, 2014). "The increased secretase-α processing of APP and resulting higher levels of the neurotrophic and myelinotrophic soluble sAPPα have been proposed to contribute to development of autism symptoms." (PMID 37305553, 2023). "FMRP and hnRNPC regulate the imbalance between total secreted APP (s-APPα), and Aβ indicates a disturbed iron balance, disrupted neuron density, and inter-neuron transmission, resulting in autism." (PMID 34827633, 2021). "Alterations of APP processing in autism result in higher levels of not only N-tr-Aβ but also secreted APP-α." (PMID 32345355, 2020). "Autism is associated with dysregulation of certain basic cellular homeostatic mechanisms, as indicated by altered processing of amyloid-β precursor protein (APP) detected in children with autism." (PMID 32345355, 2020). "Products of APP processing — N-terminally truncated amyloid-β peptide (N-tr-Aβ) species — are accumulated in autism in neurons and glia in the cortex, cerebellum, and subcortical structures of the brain." (PMID 32345355, 2020). "We propose that dysregulation in the APP mRNA gene similarly can result in different disorders: AD and autism." (PMID 27212113, 2016). "There is overlap among APP pathways, FMRP targets, and several autism-associated genes across the three networks." (PMID 27212113, 2016). "Elevated levels of secreted amyloid precursor protein-alpha (sAPPα), the product of α-secretase cleavage of APP, are found in the plasma of some individuals with autism." (PMID 23840007, 2013). "Of particular interest to autism research, we, and others, have determined that the cleavage product of APP, sAPPα, is elevated in plasma from autistic subjects vs. neurotypical and mildly autistic subjects." (PMID 23801940, 2013). "Studies have demonstrated significantly elevated levels of secreted APP and its cleavage products, including beta amyloid (Aβ), in individuals with autism." (PMID 23803181, 2013).
autism (continued). "Children with severe autism and aggression have been shown to express at least twice as much APP when compared with control children and four times as much APP when compared to children with mild autism." (PMID 23803181, 2013). "It has been proposed that increased processing of APP by secretases-α may contribute to development of autism symptoms." (PMID 32345355, 2020). "Hence, an increased processing of APP by alpha-secretases has been proposed to contribute to autism." (PMID 24252310, 2013). "Finally, since it appears that APP’s involvement in autism is part of a multi-partner network, we extend this concept into the inherently interactive realm of epigenetics." (PMID 23801940, 2013). "Altered metabolism of amyloid precursor protein (APP) in autism is indicated by higher plasma levels of secreted APP—two or more times—in children with severe autism and aggression than in children without autism, and by lower levels of amyloid-beta (Aβ) 40 than in controls." (PMID 24252310, 2013). "In this way, APP activates both trophic (through sAPPα) and apoptotic (through Aβ) pathways, and the predominance of one may determine pathology: autism vs. AD." (PMID 23801940, 2013). "In the case of APP, loss of function would favor the amyloidogenic pathway leading to AD while gain of function toxicity would favor the non-amyloidogenic pathway leading to excessive ADAM17, sAPPα, and brain overgrowth associated with autism." (PMID 23801940, 2013). "This may be another APP-related mechanism of GABAergic dysregulation in autism." (PMID 32345355, 2020). "Because Aβ accumulated in the brain in autism appears to be N-terminally truncated, and the main product of α-secretase cleavage of APP is the peptide with N-terminal aminoacid-11 — glutamic acid — we also tested the hypothesis that neurons in autism accumulate pyroglutamate-11–modified Aβ." (PMID 32345355, 2020). "This excess of APP may result in decreased neural pruning and increased neural proliferation, helping to account for the presence of long, immature dendrites of neurons from patients with autism and FXS." (PMID 23803181, 2013). "Therefore, the location of APP at the synapse and its developmental function in migration and suppression of cell adhesion support the hypothesis that dysregulated levels of APP contribute to unguided brain growth as seen in autism." (PMID 23801940, 2013). "The altered expression of proteins that may contribute to altered dendritic protein translation (homer 1), altered dendritic morphology (APP and RAC1), and receptor subunit expression (STEP), potentially contribute to the cognitive and behavioral impairments associated with autism and FXS." (PMID 23803181, 2013). "APP, which was decreased in ALS in our study, has been proposed to be involved in several human neurodegenerative diseases such as AD, autism, fragile X syndrome (FXS), ALS, multiple sclerosis (MS), and Lesch–Nyhan disease (LND)." (PMID 37238921, 2023). "Interestingly, while most neurodegeneration-related risk genes, such as APP and SOD1, are usually associated with a specific disease, GRN mutations and polymorphisms appear to be involved in a diverse group of neurological conditions, ranging from FTLD to ALS, AD, PD and even autism." (PMID 36009452, 2022). "There were significant increases in RAC1, APP 120 kDa and APP 80 kDa proteins in BA9 of children with autism vs. healthy controls." (PMID 23803181, 2013). "Taken together, the results of current postmortem studies provide novel evidence that targets of FMRP and mGluR5 signaling (RAC1, homer 1, APP, and STEP) display altered expression in the cerebellar vermis and BA9 of people with autism." (PMID 23803181, 2013). "Our current results, particularly the increased expression of APP 120 kDa and 88 kDa in BA9 of children with autism, verify these earlier findings." (PMID 23803181, 2013).
autism (continued). "In the vermis of adult subjects with autism, RAC1 was significantly increased while APP 120, STEP 66 kDa, STEP 27 kDa, and homer 1 were significantly decreased when compared with healthy controls." (PMID 23803181, 2013). "Plasma levels of secreted APP were reported to be two or more times higher in children with severe autism and aggressive behavior than in children without autism and up to four times higher than in children with mild autism." (PMID 37305553, 2023). "Forebrain specific triple knockout mice lacking APP and the two related APLPs show features of autism‐like behavior including altered social communication and interaction." (PMID 34008862, 2021). "Although the elevated level of s-AAPα is associated with autism, an overall increase in the synthesis of APP is not found in autism." (PMID 34827633, 2021). "To summarize, overall levels of processed APP are increased in FXS with autism symptoms but not idiopathic autism vs. controls." (PMID 27212113, 2016). "Recent studies revealed enhanced non-amyloidogenic cleavage of APP with α and γ secretases in such developmental disorders as autism and fragile X syndrome (FXS)." (PMID 25595448, 2015). "Experimental studies in Fmr1KO mice suggest that over-expression of APP/Aβ may contribute to the seizures observed in autism and FXS and that both the over- and under-expression of APP and its metabolites increase the incidence of seizures." (PMID 22567102, 2012). "Groups focused on molecular pathways in Autism and FXS suggest that activation of mGluR5 removes the repressive effect of the FMRP on amyloid precursor protein (APP) mRNA translation and stimulates secretion of APP, the precursor to Aβ peptide generation." (PMID 23205012, 2012). "We did not observe alterations in levels of homer 1 or APP 88 kDa in the cerebellar vermis of adults with autism and there were no significant changes for any of the proteins in the cerebellar vermis of children with autism." (PMID 23803181, 2013). "APP’s location at synaptic dendrites, its regulation by translation repressors such as FMRP, its participation in post-translational modification, and its role in neurogenesis and migration make it a prime candidate to contribute to the synaptic disruption in autism." (PMID 23801940, 2013). "Finally, to address the function of APP-in the anabolic hypothesis, while evidence exists for levels of anabolic forms of APP (e.g., sAPPα) to contribute to autism, as we have outlined herein, no specific genetic link has as of yet been reported in the literature." (PMID 23801940, 2013).
Huntington disease (35 papers, 2009 to 2025). Huntington disease (HD) is a rare neurodegenerative disorder of the central nervous system characterized by unwanted choreatic movements, behavioral and psychiatric disturbances and dementia. "It is also interesting to mention that unsupervised analysis uncovered a module with genes associated with Huntington’s disease that co-varied the same way as in Tau A2A mice (i.e. downregulation), whereas they showed an opposite variation in APP/PS1 A2A mice (i.e. upregulation)." (PMID 38964748, 2024). "Source genes tend to be specified with each disease pathway, such as APP for AD and Htt for Huntington’s disease." (PMID 30760209, 2019). "Besides, several proteins including calbindin D, amyloid precursor protein (APP), S100B, and synuclein-alpha (α-synuclein) have been ascertained in neurodegenerative diseases such as AD, Huntington’s disease (HD), multiple sclerosis, and MSA." (PMID 33958996, 2021). "We and others have shown that wild-type huntingtin (HTT), but not the polyglutamine-expanded HTT that causes Huntington’s disease (HD), facilitates APP transport by increasing the velocity of APP-containing vesicles." (PMID 32452382, 2020). "Having previously shown that Huntingtin (HTT), the scaffolding protein involved in Huntington’s disease, regulates neuritic transport of APP, we used a microfluidic corticocortical neuronal network-on-a-chip to examine APP transport and localization to the pre- and post-synaptic compartments." (PMID 32452382, 2020). "Importantly, we show that short-term EE in APP mice recovers normal dendritic morphology of Dcx cells, an effect previously observed in a mouse model of Huntington's disease." (PMID 21347380, 2011). "Furthermore, the APP/TrkA interaction is specifically lost in AD, but not in other neurodegenerative diseases such as Huntington’s disease (HD)." (PMID 28632177, 2017).